SRSF7 (serine and arginine rich splicing factor 7)
Description:
Required for pre-mRNA splicing. Can also modulate alternative splicing in vitro. Represses the splicing of MAPT/Tau exon 10. May function as export adapter involved in mRNA nuclear export such as of histone H2A. Binds mRNA which is thought to be transferred to the NXF1-NXT1 heterodimer for export (TAP/NXF1 pathway); enhances NXF1-NXT1 RNA-binding activity. RNA-binding is semi-sequence specific.
Synonyms: SFRS7; 9G8; ZCRB2; HSSG1; AAG3; RBM37; ZCCHC20
Tractability: PROTAC: UniProt records ubiquitination sites on it; ubiquitination databases record sites on it; its protein half-life has been measured.
Gene: Protein-coding gene on chromosome 2 (38,743,599 to 38,751,494, reverse strand). Ensembl gene ENSG00000115875.
Subcellular location: Nucleus; Cytoplasm
Subcellular location (Human Protein Atlas): Nucleoplasm
Pathways (Reactome):
Metabolism of RNA: Processing of Capped Intron-Containing Pre-mRNA; Transport of Mature mRNA derived from an Intron-Containing Transcript; mRNA 3'-end processing; mRNA Polyadenylation; mRNA Splicing - Major Pathway; mRNA Splicing - Minor Pathway
Disease: Dengue Virus-Host Interactions
Gene Ontology:
Molecular function: protein binding; protein domain specific binding; RNA binding; nucleic acid binding; zinc ion binding
Biological process: negative regulation of mRNA splicing, via spliceosome; RNA splicing; mRNA processing; regulation of alternative mRNA splicing, via spliceosome
Cellular component: extracellular exosome; nucleoplasm; nucleus; cytoplasm
Genetic constraint (gnomAD): Loss-of-function variants: 15 observed, 42.38 expected, observed/expected ratio (o/e) 0.35, 90% interval 0.24 to 0.55. The upper end of that interval is the gene's LOEUF score, 0.55, which puts it in group 2 of 6, group 1 being the genes least tolerant of losing a copy. Missense variants: 181 observed, 317.9 expected, observed/expected ratio (o/e) 0.57, 90% interval 0.5 to 0.64. Synonymous variants: 138 observed, 114.32 expected, observed/expected ratio (o/e) 1.21, 90% interval 1.05 to 1.39.
Homologues: Orthologues: chimpanzee SRSF7 (100% identical), macaque SRSF7 (100% identical), guinea pig SRSF7 (99% identical), dog SRSF7 (98% identical), mouse Srsf7 (98% identical), pig SRSF7 (98% identical), rat Srsf7 (98% identical), tropical clawed frog srsf7 (89% identical), zebrafish srsf7b (54% identical), Drosophila melanogaster x16 (46% identical), Drosophila melanogaster Rbp1-like (32% identical), Drosophila melanogaster Rbp1 (26% identical). Paralogues in human: SRSF3 (45% identical), SRSF4 (45% identical), SRSF6 (42% identical), SRSF1 (38% identical), SRSF5 (34% identical), SRSF9 (31% identical), RSRC2 (23% identical), RSRP1 (21% identical).